HOXA11 (homeobox A11)
Description:
Sequence-specific transcription factor which is part of a developmental regulatory system that provides cells with specific positional identities on the anterior-posterior axis.
Synonyms: HOX1I; HOX1; RUSAT1
Tractability: PROTAC: ubiquitination databases record sites on it.
Gene: Protein-coding gene on chromosome 7 (27,181,157 to 27,185,232, reverse strand). Ensembl gene ENSG00000005073.
Subcellular location: Nucleus
Subcellular location (Human Protein Atlas): Nucleoplasm
Pathways (Reactome):
Developmental Biology: Formation of the ureteric bud
Gene Ontology:
Molecular function: sequence-specific double-stranded DNA binding; DNA-binding transcription factor activity, RNA polymerase II-specific; RNA polymerase II cis-regulatory region sequence-specific DNA binding; DNA binding
Biological process: anatomical structure morphogenesis; branching involved in ureteric bud morphogenesis; cartilage development involved in endochondral bone morphogenesis; developmental growth; dorsal/ventral pattern formation; embryonic limb morphogenesis; embryonic skeletal joint morphogenesis; mesodermal cell fate specification; positive regulation of cell development; positive regulation of chondrocyte differentiation; positive regulation of DNA-templated transcription; regulation of transcription by RNA polymerase II; skeletal system development; prostate gland development; regulation of DNA-templated transcription; response to estrogen; response to testosterone
Cellular component: nucleoplasm; nucleus; protein-containing complex; protein-DNA complex; transcription regulator complex
Genetic constraint (gnomAD): Loss-of-function variants: 6 observed, 19.57 expected, observed/expected ratio (o/e) 0.31, 90% interval 0.17 to 0.61. The upper end of that interval is the gene's LOEUF score, 0.61, which puts it in group 2 of 6, group 1 being the genes least tolerant of losing a copy. Missense variants: 358 observed, 401.23 expected, observed/expected ratio (o/e) 0.89, 90% interval 0.82 to 0.97. Synonymous variants: 189 observed, 174.25 expected, observed/expected ratio (o/e) 1.08, 90% interval 0.96 to 1.22.
Gene-disease validity (ClinGen):
ClinGen rates the evidence that HOXA11 causes each of these diseases.
radioulnar synostosis with amegakaryocytic thrombocytopenia 1 (autosomal dominant): Limited.
Cancer hallmarks: invasion and metastasis (suppresses); suppression of growth (promotes); escaping programmed cell death (suppresses); proliferative signalling (promotes)
Homologues: Orthologues: chimpanzee HOXA11 (100% identical), macaque HOXA11 (99% identical), guinea pig HOXA11 (98% identical), pig HOXA11 (98% identical), rabbit HOXA11 (97% identical), mouse Hoxa11 (97% identical), rat Hoxa11 (97% identical), dog HOXA11 (85% identical), zebrafish hoxa11b (64% identical), zebrafish hoxa11a (61% identical). Paralogues in human: HOXD11 (52% identical), HOXC11 (49% identical), HOXA13 (24% identical), HOXC13 (22% identical), HOXD13 (22% identical), HOXD10 (21% identical), HOXB13 (20% identical), HOXD9 (20% identical), HOXA10 (19% identical), HOXB9 (19% identical), HOXB2 (18% identical), HOXC10 (18% identical), and 30 more.
Diseases named in the same sentence as HOXA11 in open-access papers:
HOXA11 is named in the same sentence as 82 diseases in open-access papers, as found by Europe PMC text mining. Sharing a sentence is not in itself a finding about the gene and the disease. The quoted sentences say what the papers report.
endometriosis (21 papers, 2012 to 2026). The growth of functional endometrial tissue in anatomic sites outside the uterine body. "Studies have found that the DES-induced mouse endometriosis model leads to the loss of HOXA11 expression." (PMID 40362361, 2025). "The dysregulation of HOXA genes, particularly HOXA10 and HOXA11, plays a crucial role in the pathophysiology of several uterine conditions associated with female infertility, such as EPs, endometriosis, and leiomyomas." (PMID 40305321, 2025). "This review highlights the molecular underpinnings of HOXA10/HOXA11 in reproductive health and their dysregulation in benign pathologies associated with infertility, such as endometriosis, adenomyosis, and endometrial polyps." (PMID 40305321, 2025). "The HOXA10 and HOXA11 genes regulating in-uterine embryogenesis and the regulation of ER are involved in the pathogenesis of infertility associated with endometriosis." (PMID 41153447, 2025). "For example, alternation of HOXA10 and HOXA11 expression has been identified as a mechanism of infertility associated with endometriosis." (PMID 33667269, 2021). "Hoxa11 expression has also been implicated in human implantation, and several studies have shown uterine Hoxa11 expression to be decreased in conditions associated with pregnancy failure, such as submucosal leiomyomas, endometriosis, and pregnancy loss." (PMID 31513564, 2019). "We observed that decreased HOXA11 expression was associated with hypermethylation of HOXA11 CpG rich regions in eutopic mid-secretory endometrium from infertile women with endometriosis compared to fertile women." (PMID 22233680, 2012). "The deficient expression of HOXA10 and HOXA11 in infertile women with endometriosis and in animal models has been demonstrated." (PMID 22233680, 2012). "A decrease in HOXA11 expression in eutopic mid-secretory endometrium has been found in women with endometriosis-associated infertility." (PMID 22233680, 2012). "We suggest that decreased expression of HOXA10/HOXA11 in endometrial stromal cells may be a causal factor in the development of endometriosis." (PMID 32850789, 2020). "This may indicate that changes in HOXA11 expression in eutopic endometrium throughout the implantation window can be one of the possible molecular mechanisms of endometriosis-associated infertility in women." (PMID 22233680, 2012). "Moreover, we found that DNA hypermethylation can be one of the possible molecular mechanisms causing a decrease in HOXA11 expression in the eutopic mid-secretory endometrium in infertile women with endometriosis." (PMID 22233680, 2012). "We confirmed that reduced HOXA11 expression may contribute to endometriosis-associated infertility." (PMID 22233680, 2012). "However, it is still unclear whether the observed decreased expression of the HOXA11 gene can be related to its hypermethylation in endometriosis-associated infertility." (PMID 22233680, 2012). "Further studies to evaluate the expression pattern of HOXA10/HOXA11 allowed for the presentation of DNA methylation as a possible mechanism of altered gene expression in endometriosis." (PMID 41153447, 2025). "Immunomodulation therapy alters the expression of HOXA10 and HOXA11, which would improve the implantation microenvironment in endometriosis and other inflammatory diseases that interfere with the proper regulation of the HOXA10 and HOXA11 genes." (PMID 40305321, 2025). "Endometrial polyps (EPs), endometriosis, polycystic ovarian syndrome (PCOS), leiomyoma, and hydrosalpinx are associated with both the altered expression of HOXA10 and HOXA11 and infertility." (PMID 40305321, 2025). "In mice with apparently normal endometrium, endometrial expression of Hoxa10, Hoxa11 and Igfbp1 (Insulin-like growth factor binding protein-1) was significantly reduced 14 weeks after the induction of endometriosis." (PMID 36830705, 2023).
endometriosis (continued). "HOXA11 is detected at significantly lower levels (mRNA and protein) in the eutopic mid-secretory endometrium of infertile patients with endometriosis than in endometrium of fertile women." (PMID 32063886, 2019). "In particular, the role of transcription factors HOXA10 and HOXA11 and their downstream genes in endometriosis and related infertility has been shown." (PMID 22952593, 2012). "In the group of eighteen infertile women with endometriosis, we found fifteen (83.3%) individuals with methylation in HOXA11 region II." (PMID 22233680, 2012). "We used RQ-PCR and western blotting analysis to evaluate HOXA11 transcript and protein levels, respectively, in eutopic mid-secretory endometrium from infertile women with endometriosis, fertile women and women with tubal occlusion." (PMID 22233680, 2012). "We also found significantly reduced HOXA11 protein levels in eutopic endometrium from infertile women with endometriosis than in fertile women (p = 0.004) and women with tubal occlusion (p = 0.001)." (PMID 22233680, 2012). "We observed significantly lower levels of HOXA11 transcript in women with endometriosis as compared to fertile women (p = 0.003) and women with tubal occlusion (p = 0.041)." (PMID 22233680, 2012). "There were significantly lower levels of HOXA11 transcripts (p = 0.003, p = 0.041) and protein (p = 0.004, p = 0.001) in women with endometriosis as compared to fertile women and infertile women with tubal occlusion." (PMID 22233680, 2012). "In present study we confirmed that both HOXA11 mRNA and protein levels were significantly decreased in eutopic mid-luteal endometrium in infertile women with endometriosis as compared to fertile women." (PMID 22233680, 2012). "Additionally, melatonin has been shown to increase the expression of genes like LIF, HOXA10, and HOXA11 in endometriosis mice." (PMID 39409719, 2024). "The HOX genes remain important in adulthood; HOXA11 has also been implicated in endometriosis-associated infertility, as it fails to rise in patients with endometriosis during the implantation window and secretory phase." (PMID 37410157, 2023). "Based on mouse comparative studies, it was suggested that impaired endometrial receptivity in the endometriosis group may be caused by altered gene expression due to methylation of the homeobox protein A10 (HOXA10) and A11 (HOXA11)." (PMID 33411206, 2021). "A number of implantation markers such as αvβ3 integrin, LIF, homeobox A10 (HOXA10) and HOXA11 are aberrantly expressed in patients with endometriosis and may contribute to infertility in some women with endometriosis." (PMID 34149619, 2021). "We want to pay special attention to the relation of impaired expression of HOXA10 and HOXA11 to endometriosis since this disease involves the ability of the endometrial stroma to self-organize ectopically, i.e., to “ignore” conditions of an ectopic environment." (PMID 32850789, 2020). "Obtained results indicate the relation of HOXA11 with infertility in endometriosis." (PMID 32063886, 2019). "HOXA10 and HOXA11 are known to be differentially methylated in endometriosis." (PMID 24603652, 2014). "Moreover, we found significantly higher methylation levels of the CpG region in the first exon of HOXA11 in infertile women with endometriosis compared with fertile women (p < 0.001) and infertile women with tubal occlusion (p < 0.001)." (PMID 22233680, 2012). "Our bisulfite DNA sequencing of HOXA11 CpG rich region II showed significantly increased levels of DNA methylation in eutopic mid-secretory endometrium from infertile women with minimal endometriosis as compared to fertile women." (PMID 22233680, 2012). "However, little is know about effect of HOXA11 gene methylation on its expression in infertile women with endometriosis." (PMID 22233680, 2012).
endometriosis (continued). "However, we found significantly higher methylation levels of HOXA11 region in II the in eutopic mid-secretory endometrium obtained from infertile women with endometriosis as compared to material obtained from the fertile women (p < 0.001) and women with tubal occlusion (p < 0.001)." (PMID 22233680, 2012). "Therefore we studied the effect of DNA regulatory sequences' methylation on the HOXA11 transcript and protein levels in eighteen infertile women with minimal endometriosis, sixteen fertile women and sixteen infertile women with fallopian tubal occlusion from a Polish cohort." (PMID 22233680, 2012). "This study aimed to evaluate compartment-specific immunohistochemical expression patterns of HOXA-10, HOXA-11, CD44, β1 integrin, ECM-1, and focal adhesion kinase (FAK) in women with endometriosis-related implantation failure." (PMID 42010698, 2026). "Endometrial expression of Hoxa10, Hoxa11, Igfbp1, Klf9 (Kruppel-like factor 9) and PGR was reduced in mice when endometriosis was induced in the peritoneal cavity (proximal) compared to control eutopic endometrium." (PMID 36830705, 2023). "During the last decade, several studies have reported abnormal methylation patterns of selected genes, e.g. steroidogenic factor 1, progesterone receptor B, oestrogen receptor-β, HOXA10, HOXA11, COX-2 and aromatase, in endometriotic lesions and endometria of endometriosis patients." (PMID 26759613, 2016). "The expression of HOXA10 and HOXA11 genes were decreased during the secretory phase of endometrium in some nonoptimal conditions such as in adenomyosis, endometriosis, myoma idiopatic infertility." (PMID 24639724, 2013). "This increase in HOXA10 and HOXA11 levels is not observed in patients with endometriosis." (PMID 33411206, 2021). "There was no DNA methylation in HOXA11 regions I and III in all infertile women with endometriosis and all fertile women and women with tubal occlusion." (PMID 22233680, 2012).
ovarian carcinoma (18 papers, 2009 to 2023). A malignant neoplasm originating from the surface ovarian epithelium. "HOXA10 and HOXA11 genes show significant DNA methylation differences in ovarian cancer, with HOXA11 methylation associated with poor prognosis and residual tumor." (PMID 37629546, 2023). "Although HOXA11 DNA methylation was observed to correlate in the progression of ovarian cancer, little is known about the molecular mechanisms underlying cervical cancer." (PMID 27792998, 2016). "Epigenetic silencing of HOXA11 has been observed in a number of tumors including ovarian cancer; it is associated with a worse prognosis and/or chemotherapy resistance." (PMID 26893359, 2016). "HOXA11 hypermethylation is also known to be strongly associated with the residual tumor after cytoreductive surgery in ovarian cancer, and with poor outcome." (PMID 24259349, 2013). "Recently, it has been demonstrated that HOXA11 DNA methylation is significantly associated with residual tumors after cytoreductive surgery and is a marker independently associated with poor outcome in ovarian cancer." (PMID 22233680, 2012). "Another study found that lncRNA HOXA11.AS knockdown increased the expression of autophagy-related proteins and improved cisplatin sensitivity, decreased ovarian cancer cell proliferation, and promoted cell apoptosis." (PMID 36739404, 2023). "Overexpression of HOXA11 has been observed in ovarian cancer, bladder cancer, renal cell carcinoma and lung cancer, while downregulation of HOXA11 has been observed in gastric cancer and glioblastoma." (PMID 32296636, 2020). "Recently, hypermethylation of HOXA11 is uncovered in ovarian cancer, lung cancer, gastric cancer and breast cancer." (PMID 28038461, 2017). "The hypermethylation of HOXA11 is an unfavorable prognostic biomarker in several cancers, especially in the female hormone dependent cancers such as ovarian cancer and endometrial adenocarcinoma." (PMID 28038461, 2017). "Hypermethylation and low expression of HOXA11 was reported in different cancers, such as ovarian cancer and endometrial cancer, and it functions as a tumor suppressor." (PMID 28423531, 2017). "Demthylation treatment with decitabine restored HOXA11 sensitivity to platinum in patients with platinum-resistant ovarian cancer in a Phase II clinical trial." (PMID 28423531, 2017). "Several cancers that overexpress HOXA11 include epithelial ovarian cancers, bladder cancer, cervical cancer and glioma." (PMID 27792998, 2016). "Among HOXA genes, HOXA11 hypermethylation has recently been reported in lung cancer, ovarian cancer, glioblastoma multiforme, follicular lymphoma, endometrial adenocarcinoma and cervical cancer." (PMID 24259349, 2013). "Homeobox A10 (HOXA10) and Homeobox A11 (HOXA11) have previously been shown to be overexpressed in ovarian cancers, and play a role in stimulating tumor growth and determining the histologic identity of epithelial ovarian cancers." (PMID 22371431, 2012). "The homeobox transcription factor genes HOXA7, HOXA9, HOXA10, and HOXA11 have an important role in the morphologic heterogeneity of epithelial ovarian cancers and their assumption of mullerian-like features." (PMID 20145720, 2009). "HOXA11 has been notably over-expressed in epithelial ovarian cancers." (PMID 29914539, 2018). "In ovarian cancer, the methylation of HOXA11 has been reported to be a poor prognostic marker." (PMID 28423531, 2017). "In addition, HOXA11 hypermethylation was detected in normal endometrium from premenopausal ovarian cancer patients, suggesting that HOXA11 hypermethylation can be a predictive marker for ovarian cancer." (PMID 24259349, 2013). "There is clear evidence for this in ovarian cancer where the expression of HOXA9, HOXA10 or HOXA11 confer a serous, endometrioid-like and mucinous-like phenotype respectively." (PMID 20219106, 2010).
ovarian carcinoma (continued). "The study found that in the patients with ovarian cancer, the normal endometrial tissue showed hypermethylation of HOXA9 and HOXA11 but this was not the case in patients without cancer." (PMID 31382546, 2019).